ENSG00000201042
Synonyms: LOC124900328
Gene: Small nucleolar RNA gene on chromosome 12 (118,888,434 to 118,888,564, reverse strand). Ensembl gene ENSG00000201042.
Gene Ontology:
Biological process: RNA processing
Cellular component: Cajal body; nucleolus
Homologues: Orthologues: mouse Gm22944 (69% identical), rat LOC120101256 (60% identical). Paralogues in human: SNORA38B (93% identical), SNORA38 (80% identical).